MOG (myelin oligodendrocyte glycoprotein)
Diseases named in the same sentence as MOG in open-access papers (continued):
Sharing a sentence is not in itself a finding about the gene and the disease.
myelitis (continued). "Crucially, the absence of CSF pleocytosis, autoantibodies (AQP4/MOG/MBP), and demyelinating markers differentiated this case from myelitis, while DSA confirmed the vascular etiology." (PMID 41137336, 2025). "Most studies have found MOG-IgG exclusively in patients with ON and/or myelitis who are negative for AQP4-IgG, suggesting that MOG-IgG may denote a disease entity in its own right." (PMID 27788675, 2016).
autoimmune disease (106 papers, 2007 to 2025). A disorder resulting from loss of function or tissue destruction of an organ or multiple organs, arising from humoral or cellular immune responses of the individual to their own tissue constituents. "MOGAD, a serious autoimmune disorder involving antibodies against MOG, causes high rates of disability and relapse, and predominantly affects the optic nerve and spinal cord." (PMID 40791909, 2025). "Myelin oligodendrocyte glycoprotein antibody‐associated disease (MOGAD) is a rare autoimmune disease caused by MOG antibodies that can lead to demyelination of the central nervous system, mainly affecting the optic nerve, spinal cord, meninges, and brain stem." (PMID 40103700, 2025). "An important differential diagnosis to NMOSD is constituted by MOG encephalomyelitis (MOG-EM) or MOG antibody-associated autoimmune disorders (MOG-AD); this distinct disease was defined after the discovery of MOG-IgG." (PMID 36472724, 2024). "Such an antigen has been identified in autoimmune diseases associated with autoantigens—for example, the basic protein transgenic myelin oligodendrocyte glycoprotein (MOG) in MS." (PMID 34361038, 2021). "Neuromyelitis optica/Devic’s disease is an autoimmune disease involving the spinal cord and optic nerve that is associated with autoantibodies against aquaporin-4 and interestingly antibodies against MOG." (PMID 24223903, 2013). "The predisposition of B6/Rab4AQ72L mice to MOG-induced EAE indicates that Rab4A activation may broadly enhance CD4+ T cell-dependent autoimmune diseases, including MS106." (PMID 38519468, 2024). "According to DO enrichment analysis, the AQP4-ON group was mainly associated with atherosclerosis, arteriosclerotic cardiovascular disease and arteriosclerosis, while the MOG-ON group was associated with Alzheimer’s disease, hypersensitivity reaction type II disease and rheumatoid arthritis." (PMID 36969199, 2023). "The autoimmune disease against MOG is called MOG antibody (MOG-IgG)-associated disease." (PMID 36648967, 2022). "This may reflect instability or apoptosis of Tregs induced by rh-MOG that may subsequently contribute to a probable loss of tolerance toward MOG autoantigen in MOGR which may explain relapses in this recurrent pediatric autoimmune disease." (PMID 34220827, 2021). "Thus, in contrast to non-autoimmune mice, in Th mice, the concentration of antibodies against DNA, MBP, and MOG increases in time, as in the case of other animals predisposed to the development of spontaneous autoimmune diseases." (PMID 33595783, 2021). "The opposite response of Tregs to rh-MOG in MOGNR, where CD4+ Tregs increased, and in MOGR, where CD45RA-Foxp3+ Tregs decreased, suggests a probable loss of tolerance toward MOG autoantigen in MOGR which may explain relapses in this recurrent pediatric autoimmune disease." (PMID 34220827, 2021). "EAE is an autoimmune disease animal model induced by immunization with MOG protein, widely used in studying the pathological mechanisms of multiple sclerosis (MS)." (PMID 40463369, 2025). "While this study demonstrated the natural targeting ability and immunomodulatory effects of AE using MOG as an antigen model, these exosomes can be utilized with different antigens, making them suitable for treating various autoimmune diseases." (PMID 39937659, 2025). "Understanding how miR-155 affects the immune response to MOG can help in identifying new targets for intervention and contribute to advancing our knowledge of autoimmune disease pathogenesis." (PMID 39518908, 2024). "We also considered the possibility of MOG antibody disease, a recently identified autoimmune disorder with a preference for optic nerve and spinal cord involvement." (PMID 39618752, 2024). "We have previously shown that MOG-specific B cells are potent antigen-presenting cells that are crucial to drive T cell proliferation and induce spontaneous autoimmune disease." (PMID 38057803, 2023).
autoimmune disease (continued). "We found that the research topics “COVID-19”, “neuroinflammation”, and “myelin oligodendrocyte glycoprotein” have received attention in recent years due to the COVID-19 pandemic, which has been a challenge for patients with autoimmune diseases." (PMID 37346048, 2023). "This further highlights the role of complement in AQP4-IgG–mediated disease and diminishes the importance of complement activation in MOG-IgG–mediated autoimmune disease." (PMID 36414427, 2023). "Together, these findings further underline the more pronounced role of complement activation in autoimmune diseases directed against AQP4 compared with MOG." (PMID 36414427, 2023). "In the context of treating MS and other autoimmune diseases, we expect that the co-delivery of MOG, GpG, and Rapamycin will robustly downregulate proinflammatory cues to drive naïve T cells towards regulatory phenotypes." (PMID 36814918, 2023). "In this study, we evaluated the potential of platelet-specific MOG expression in immune tolerance induction in an EAE model of autoimmune disease." (PMID 36389708, 2022). "Our results suggest that the pathomechanisms of MOG-Ab production are different from those of AQP4-Ab positive NMOSD, in which the pathogenic autoantibody is continuously produced and other coexisting autoimmune diseases occur more frequently than MOG-AD." (PMID 34991631, 2022). "At present, the treatment protocols for patients with MOG-abs are mostly based on limited retrospective research and treatment experience from other autoimmune diseases, such as AQP4-ab-positive NMOSD." (PMID 33841310, 2021). "Our results show that Seldegs can ameliorate disease mediated by MOG-specific antibodies and indicate that this approach also has the potential to treat other autoimmune diseases where the specific clearance of antibodies is required." (PMID 33212299, 2021). "Although the frequency of coexistent autoimmune diseases seems to be lower than AQP4‐Ab‐positive patients, comorbidity with other autoimmune disorders has been reported in MOG‐EM patients." (PMID 33319460, 2021). "Myelin oligodendrocyte glycoprotein antibody disease (MOGAD) is a rare autoimmune disorder characterized by antibodies against the myelin oligodendrocyte glycoprotein (MOG) and has a wide spectrum of presenting clinical phenotypes." (PMID 34975841, 2021). "Our findings are important for the differential diagnosis of pediatric MS and MOG-EM and add to the understanding of the immunopathogenesis of this newly described autoimmune disease." (PMID 32883358, 2020). "Our findings are important for the differential diagnosis of MS and MOG-EM and add to the understanding of the immunopathogenesis of this newly described autoimmune disease." (PMID 32883348, 2020). "EAE is a CD4+ T-helper (Th)-cell-mediated autoimmune disease in rodents induced by immunization with CNS-specific antigens such as myelin oligodendrocyte glycoprotein (MOG)." (PMID 30621022, 2019). "In MOG-EM, the frequency of coexistent autoimmune diseases seems to be lower than reported for AQP4-Ab positive patients." (PMID 30405519, 2018). "Our study indicates that Hrd1 is a potential therapeutic target for autoimmune disease treatment because genetic suppression of Hrd1 in T cells protected mice from MOG-induced EAE." (PMID 27417417, 2016). "In C57BL/6 mice, EAE is a CD4+ T cell driven autoimmune disease in response to peripheral inoculation with myelin oligodendrocyte glycoprotein (MOG) protein or peptide." (PMID 26075905, 2015). "We followed mice bearing mutant TCR and BCR specific for MOG autoantigen for the development of CNS autoimmune disease." (PMID 26441975, 2015). "This study investigates whether exosomes derived from anti‐inflammatory macrophages (AE) and decorated with myelin oligodendrocyte glycoprotein (MOG) peptide (AE/M) can induce immune tolerance in autoimmune diseases." (PMID 39937659, 2025).
autoimmune disease (continued). "Although headache is not mentioned as an early symptom of MS, some studies have shown a higher prevalence and higher risk of headache in autoimmune diseases including MS, neuromyelitis optica (NMO), and myelin oligodendrocyte glycoprotein (MOG) compared with healthy individuals." (PMID 39825368, 2025). "Moreover, demyelination in the context of autoimmune diseases due to antibodies produced against MOG and MAG has been identified." (PMID 35652161, 2022). "Eventually, this led to a life-long tolerance to MOG-induced autoimmune disease." (PMID 34149706, 2021). "Our observation that Ncf1-deficient mice are protected from IRBP peptide-induced EAU is difficult to reconcile with the findings of aggravated diseases detected in the same mice induced to develop two other models of autoimmune disorders, EAE induced by MOG and arthritis caused by collagen or serum." (PMID 32380695, 2020). "Altered self through peptide modifications may lead to a bypass of thymic tolerance and triggering of autoimmune disease, as has been experimentally demonstrated for myelin oligodendrocyte glycoprotein." (PMID 28597127, 2017). "Also spontaneous models of MOG-induced CNS disease were highly informative for deciphering the role of anti-MOG responses in autoimmune disease." (PMID 28533781, 2017). "Importantly, the C57BL/6 EAE model is heavily skewed to induce autoimmune disease even with the native MOG and involves the use of complete Freund’s adjuvant and pertussis toxin in order to evoke CNS inflammation." (PMID 28828577, 2017). "But even if MOG Abs would only be a secondary immune reaction they still could be clinically relevant biomarkers such as seen in diabetes type I, an autoimmune disease affecting insulin producing β-cells in the pancreas." (PMID 28533781, 2017). "We tested whether the MOG-presenting C. utilis strain was able to reduce the severity of the autoimmune disease of the CNS in the mouse model EAE." (PMID 27159446, 2016). "In addition, 100% of WT mice developed EAE disease by day 10 after MOG immunization, while only 80% of Hrd1 cKO mice developed disease and 20% of mice were fully protected from MOG-induced autoimmune disease." (PMID 27417417, 2016). "Although our findings suggest that soluble MHC class II dimer can be used clinically to treat autoimmune disease, human MS is much more complicated than the MOG-induced EAE mouse model, where there is only a single self-peptide involved and the MHC allele is known." (PMID 23077616, 2012). "Based on the recent findings that inflammatory TH17 lymphocytes were implicated in autoimmune disease pathogenesis, conjugation of CTB to myelin oligodendrocyte glycoprotein (MOG), delivered together with Complete Freund’s Adjuvant (CFA), resulted in suppression of lymphocyte IL-17 secretion." (PMID 22069653, 2010). "However, as pathogenic MOG-abs do not recognize their antigen inside living cells, MOG-abspositive patients are spared from additional, organ-specific autoimmune diseases." (PMID 29465432, 2018). "To extend the applicability of AP-EVs to autoimmune disease models, we constructed AP-EVs particles expressing MHC II loaded with a myelin oligodendrocyte glycoprotein (MOG) peptide." (PMID 41410284, 2025). "To further confirm Treg‐mediated regulation of autoimmune disease, we depleted endogenous CD25 positive regulatory T cells using anti‐CD25‐neutralizing antibodies 3 days and 1 day prior to MOG immunization." (PMID 34306974, 2021). "The same holds true for patients treated with RTX for various autoimmune diseases and for CD20 depletion in EAE induced with MOG peptide." (PMID 33880738, 2021). "We found that TNFAIP3 serum level decrements are associated with the onset of a relapse in individual MOG-AAD patients and thus has significant potential as a biomarker and therapeutic target for MOG-AAD and other autoimmune diseases." (PMID 32709905, 2020).
autoimmune disease (continued). "Cell-based assays are useful tools for the diagnosis of potential autoimmune disease and are successfully used for targets such as GluN1 (NR1), dopamine D2 receptor (DR2), and myelin-oligodendrocyte glycoprotein." (PMID 33208725, 2020). "Myelin oligodendrocyte glycoprotein (MOG) is a minor component of the myelin sheath that is targeted by T cells and autoantibodies in autoimmune diseases of the central nervous system (CNS)." (PMID 32069316, 2020). "have shown that gut commensal bacteria can trigger a relapsing-remitting autoimmune disease driven by myelin-specific CD4+ T cells and demyelination, given the availability of MOG—the autoantigen myelin oligodendrocyte glycoprotein." (PMID 25694551, 2015). "Screening for autoimmune diseases, including MOG and AQP4 antibodies, and metabolic diseases were negative." (PMID 38138047, 2023). "MS is considered to be a predominantly T cell-mediated autoimmune disease, directed toward various myelin-derived antigens, including myelin basic protein (MBP), proteolipid protein (PLP), myelin oligodendrocyte glycoprotein (MOG), and αB-crystallin, that are expressed in the CNS." (PMID 33679769, 2021). "The coexistence of MOG-IgG and anti-NMDAR-IgG may result, firstly, from autoimmune disorders targeting oligodendrocytes." (PMID 31866928, 2019). "In our study, there was no apparent difference in the immune response or EAE, despite MOG-MDA clearly being a SRA ligand, but it is unclear whether the strong adjuvant may mask minor effects in this model of autoimmune disease." (PMID 28828577, 2017). "Together, our data demonstrated that targeting transmembrane domain-deleted MOG expression to platelets is an effective strategy to induce immune tolerance in EAE, which could be a promising approach for the treatment of patients with MS autoimmune disease." (PMID 36389708, 2022). "Demographically our patients are similar to other MOG cohorts in terms of a balanced gender distribution (64% female vs. 44–68%), onset age (29 vs. 27–37 years) and rate of comorbid autoimmune disorders (7 vs. 7–11%), but our cohort had a higher proportion of non-Caucasian patients (47 vs. 8–27%)." (PMID 33510701, 2020). "After classification of MOG‐EM likelihood groups, patients with coexisting ANA autoantibodies or another autoimmune disease were not present in the “definite” MOG‐EM group." (PMID 33047894, 2021). "In the current study, we sought to expand cross-disease autoantibody exploration to include four validated neurologic autoantibodies (MOG, AQP4, AChR, and MuSK) in nonneurologic autoimmune diseases." (PMID 30824481, 2019). "Surprisingly given their low affinity, we and many others have employed MOG-activated 2D2 T cells to induce EAE, indicating low TCR affinity for antigen does not preclude autoimmune disease." (PMID 22412888, 2012). "Autoimmune disorders, including Bickerstaff’s, ADEM, NMO, and MS, were considered but deemed less likely due to atypical clinical and radiological features, as well as negative lab findings (anti-GM1, anti-GQ1, anti-MOG, anti-AQP-4, and oligoclonal bands)." (PMID 40135036, 2025).
Autoimmunity (103 papers, 2010 to 2025). The occurrence of an immune reaction against the organism's own cells or tissues. "Sleep disorders and chorea associated with IgLON‐5 autoimmunity (p < 0.001), whereas coexisting myelopathy associated with MOG‐IgG positivity (p = 0.049)." (PMID 39708293, 2025). "Myelin oligodendrocyte glycoprotein antibody-associated disease (MOGAD) is an autoimmune disorder involving central nervous system demyelination with antibodies against myelin oligodendrocyte glycoprotein (MOG)." (PMID 40717732, 2025). "The amino acids 35–55 are buried in dimer formation, and have also been implicated in autoimmunity to MOG." (PMID 39598329, 2024). "In vivo studies have shown that microbiota from MS twins transplanted to transgenic mice with the T cell receptor specific for myelin oligodendrocyte glycoprotein (MOG), caused a higher level of autoimmunity than the microbiota obtained from healthy twins." (PMID 33322628, 2020). "Overall, our findings demonstrate that the increased susceptibility of Cblb−/− mice to a MOG-induced neuroinflammatory autoimmune reaction in vivo is mediated via GM-CSF and suggests that Cbl-b limits autoimmunity by preventing the pathogenic effects of GM-CSF overproduction in T cells." (PMID 30349541, 2018). "Autoimmunity directed against AQP4 affected overlapping and distinct CNS niches as compared with autoimmunity directed against MOG." (PMID 39934927, 2025). "Myelin oligodendrocyte glycoprotein (MOG) antibody-associated disease (MOGAD) and autoimmune glial fibrillary acidic protein (GFAP) astrocytopathy have received increasing attention in recent years." (PMID 41333477, 2025). "MBP, myelin oligodendrocyte glycoprotein (MOG), and proteolipid protein (PLP), the major constituents of the myelin sheath, have been linked with autoimmunity in the pathology and identified as autoantigens." (PMID 39407617, 2024). "For the pathogenic mechanism, it has been reported that inflammatory demyelination of cerebral ALD seems to be related to autoimmunity, such as increased serum antibody responses against myelin oligodendrocyte glycoprotein." (PMID 37360358, 2023). "This case highlights a possible association between inflammation due to COVID-19 and transient secondary autoimmunity with transient MOG antibodies and atypical clinical presentation." (PMID 34706651, 2021). "To overcome this limitation, we have developed a class of antibody-based therapeutics for the treatment of autoimmunity involving antibodies that recognize the autoantigen, myelin oligodendrocyte glycoprotein (MOG)." (PMID 33212299, 2021). "MOG-specific autoimmunity is characterized by the generation of MOG-reactive autoantibodies that can induce demyelination." (PMID 34149706, 2021). "EAE is a well-established model of autoimmunity induced by the subcutaneous injection of self-antigens derived from myelin proteins, such as the myelin oligodendrocyte glycoprotein (MOG) and the proteolipid protein (PLP)." (PMID 31937331, 2020). "In this model, autoimmunity-prone female C57BL6 mice are induced by myelin oligodendrocyte glycoprotein (MOG) to trigger autoimmune responses." (PMID 32694981, 2020). "Nowadays, MOG-IgG seropositive patients are mostly assigned to a separate disease entity called MOG-IgG autoimmunity [or MOG encephalomyelitis (MOG-EM)], although they are formally still part of the NMO spectrum." (PMID 31258505, 2019). "Previous studies had shown that coexisting autoimmunity was rare in MOG-ON patients, whereas coexisting autoimmune disorders were present in more than one-third of AQP4-ON patients." (PMID 31061727, 2019). "Specifically, antinuclear antibodies were found in only 7% of MOG-IgG patients (versus 43% of AQP4-IgG patients), and coexisting autoimmune conditions were reported in only 11% of MOG-IgG individuals (versus 45% of AQP4-IgG subjects) in another series." (PMID 29670575, 2018).